HGF (hepatocyte growth factor)
Diseases named in the same sentence as HGF in open-access papers (continued):
Sharing a sentence is not in itself a finding about the gene and the disease.
cancer (continued). "Overall our study indicated that deguelin exerted potent anti-angiogenesis activities via specifically targeting HGF-c-Met and VEGF-VEGFR pathways in cancer cells and endothelial cells, respectively." (PMID 29416603, 2018). "HGF/MET signalling has been repeatedly reported to be a critical pathway for communication between stroma and cancer cells." (PMID 29993037, 2018). "In fact, drugs that can block specific cancer cell dependent pathways such as: EGFR, BRAF, HER2, and HGF/c-Met signaling are being developed, and are predicted to have fewer side effects." (PMID 30214428, 2018). "Co-culturing of hepatocyte growth factor (HGF), the Met ligand-secreting fibroblast and cancer cells declined cancer cell sensitivity towards TKI treatment." (PMID 29455663, 2018). "MET is known to play an important role in the progression of various cancers, including RCC through activation by an active form of HGF, and high MET expression with worsening prognosis has been reported." (PMID 29890660, 2018). "Mounting evidence proved that stromal expression of soluble factors including HGF, WNT16B, and TNF-α in the TME has a significant correlation with cancer resistance to chemotherapy, radiation, and targeted agents." (PMID 30333494, 2018). "The fibroblast and endothelial cells produced HGF and EGFR ligands reduced the cancer cell response to crizotinib, a dual inhibitor of ALK and Met." (PMID 29455663, 2018). "Recent reports show that several microRNAs participate in inhibiting HGF/c-MET signaling networks through antagonizing c-MET or HGF in digestive system cancers, and the miRNAs-HGF/c-MET axis plays crucial and novel roles for cancer treatment." (PMID 30360560, 2018). "MACC1 controls hepatocyte growth factor (HGF)/Met signaling pathway and enhances migration, invasion, and metastasis of cancer cells." (PMID 30515418, 2018). "IGFs that are secreted from stromal cells can act on cancer cells via direct IGF-1R signaling, and together with hepatocyte growth factor/HGF, can phosphorylate Annexin A2/AnxA2, a protein that has a well-established role in invasion/metastasis." (PMID 29475434, 2018). "HGF and its receptor HGFR regulate normal cell growth and development in many tissue types, but they also control growth, invasion and metastasis of cancer cells." (PMID 28659168, 2017). "Adipocytes were shown to promote the proliferation of cancer cells via hepatocyte growth factor (HGF) signaling, and Wnt5a secreted by cancer cells was found to induce lipolysis." (PMID 28407685, 2017). "The established relevance of SF/HGF-MET in tumorigenesis and progression suggests that MET inhibition is a potential strategy in cancer therapy, a notion supported by a growing body of preclinical evidence." (PMID 28532501, 2017). "After activation by an extracellular protease, mature HGF transduce signals through MET receptor tyrosine kinase and induce pleiotropic effects on cancer cells, such as epithelial to mesenchymal transition (EMT), invasiveness, survival and growth." (PMID 29202869, 2017). "While autocrine HGF activation of c-Met has been reported in other cancer types, HNSCC cells fail to secrete detectable levels of the ligand, indicating the TAF supplied HGF activates c-Met in a predominantly paracrine manner." (PMID 28441771, 2017). "Within the tumor microenvironment, the shed active matriptase can activate its cancer-related substrates, including urokinase, HGF, and PDGF-D in the pericellular space, providing an important mechanism for cancer cells to interact with stromal cells." (PMID 28829816, 2017). "Since it has been reported that HGF/c-Met activated PI3K/Akt and GRP78 pathways to regulate cancer progression, we next examined the levels of c-Met/PI3K/Akt phosphorylation and GRP78 expression in both SKOV3 and HO-8910 cells." (PMID 28258248, 2017).
cancer (continued). "TAMs accordingly produce multiple growth factors (HGF, EGF, TGF, PDGF, etc.)and inflammatory cytokines (IL‐1β, IL‐6, and TNF‐α) that each can induce EMT in cancer cells." (PMID 28599100, 2017). "Cancer cells resistant to chemotherapy and oncoprotein-targeted drugs display increased IL-1α, IL-6, IL-8, TNF-α, HGF, EGF, VEGF, GM-CSF and SDF-1α expression." (PMID 28928376, 2017). "HGF levels produced by PSCs and the effects of PSC media on the cancer cells were increased by IL-1α and inhibited by TGFβ." (PMID 29069737, 2017). "Binding of HGF to its receptor c-MET on cancer cells stimulates several intracellular signalling cascades, which regulate cancer cell functions such as proliferation, migration and apoptosis." (PMID 29100344, 2017). "One of these signaling modules, HGF-c-MET, is frequently overexpressed in AVPCa and AR inhibitor treated cancers." (PMID 28103576, 2017). "Media from high-HGF-producing PSCs stimulated phosphorylation of Met, Gab1, and ERK in the cancer cells and induced increases in DNA synthesis and migration which were blocked by the Met inhibitor SU11274, indicating a role of HGF as a mediator." (PMID 29069737, 2017). "Cardiotoxin III (CTX-III), a membrane toxin from Taiwan cobra (Naja naja) venom, inhibits the migration of cancer cells by reversion of EGF- and HGF-induced EMT." (PMID 29189742, 2017). "We showed that a novel inhibitor of pro-HGF activation, SRI31215, blocks the crosstalk between cancer cells and fibroblasts and overcomes resistance to anti-MET therapy in MET-amplified NSCLC cells." (PMID 28968967, 2017). "The upstream regulators of these functions were predicted to involve the growth factors TGFB1, EGF, HGF and IGF1, which have known roles in activating these cancer progression pathways." (PMID 27965461, 2017). "The highest HGF-secreting PSC population, SC40, was also most potent in inducing cancer cell migration and DNA-synthesis." (PMID 29069737, 2017). "The HGF/c-Met/ETS-1 pathway mediates the proliferation, development, metastasis, invasion, and angiogenesis of a multitude of human cancer cells." (PMID 29312607, 2017). "The expression of HGF and c-MET was also checked in GC liver metastases and para-carcinoma tissues, and HGF is highly expressed in liver tissues but not in the metastases." (PMID 28393839, 2017). "Both HGF and fibroblasts induced the expression of vimentin in DU145 cells, confirming that they promote EMT in cancer cells." (PMID 27121052, 2016). "This activity surpassed by several fold the effects of known chemotractants for cancer cells, such as SDF-1 or HGF/SF." (PMID 27634880, 2016). "In lung cancer, CAFs promote the proliferation and invasiveness of cancer cells by high expression of Forkhead box F1 and CXCL12.CAFs from squamous cell carcinoma of the head, neck and esophagus secrete hepatocyte growth factor to promote cancer invasion." (PMID 26954362, 2016). "Aberrant HGF/MET signaling supports cell survival, proliferation, angiogenesis, invasion and metastatic spread, which are essential hallmarks of cancer." (PMID 27121052, 2016). "HGF and EGF signaling are often hyperactivated in cancer, culminating in increased motility and invasion." (PMID 27105540, 2016). "Several cancers are addicted to HGF/MET signaling, establishing both HGF and MET as valid therapeutic targets." (PMID 27121052, 2016). "The binding of HGF to its receptor MET activates signaling cascade which promotes the growth and survival of cancer cells and stimulates epithelial to mesenchymal transition (EMT), one of the early stages of metastatic spread." (PMID 27121052, 2016). "Among these CAF-secreted growth factors, HGF signaling has been shown to be involved in drug resistance through the upregulation of MAK and AKT pathways and in expansion of the cancer stem cell (CSC) population." (PMID 27391808, 2016).
cancer (continued). "We demonstrated that inhibitors of HGF activation such as SRI 31215 represent a novel approach to inhibit autocrine and paracrine oncogenic HGF/MET signaling and to prevent HGF-dependent proliferation, EMT and migration of cancer cells." (PMID 27121052, 2016). "Activation of pro-HGF is primarily driven by matriptase, hepsin and HGFA, serine proteases that are commonly overexpressed in cancer tissues." (PMID 27121052, 2016). "Aberrant HGF/MET signaling supports cell survival, proliferation, angiogenesis, invasion and metastatic spread of cancer cells, establishing HGF and MET as valid therapeutic targets." (PMID 27121052, 2016). "Analysis of the cancer cell lines shows a variable, but widespread expression of MET and FGFR2, which are receptors for HGF and FGF7, respectively, across the panel of ESCC cell lines." (PMID 25884729, 2015). "HGF/MET signaling appears to be a critical pathway in a variety of malignancies, and thus it has become a potential target for cancer therapeutics." (PMID 28536405, 2015). "Activation of CD44V6 induces expression of c-met in cancer cells and promotes development, invasion and metastasis of tumors via the CD44V6-c/met/HGF complex, which can activate c-met." (PMID 25658794, 2015). "NRP1 has been shown to promote epithelial mesenchymal transition and increase motility of endothelial cells as well as cancer cells by regulating TGF-beta, integrin and HGF/c-Met signaling." (PMID 26097868, 2015). "c-Met is a receptor tyrosine kinase that upon binding of its ligand, hepatocyte growth factor (HGF), activates downstream pathways with diverse cellular functions that are important in organ development and cancer progression." (PMID 25887320, 2015). "Next, we examined the effects of adding growth factors HGF, FGF1, FGF7, and FGF10, to the culture medium of cancer cells." (PMID 25884729, 2015). "A number of novel HGF/MET-targeting agents, either as therapeutic proteins or as small molecules, has been tested in patients with cancer, and some of them showed encouraging results in clinical studies." (PMID 28536405, 2015). "In cancer EMT, signals emanate via factors, including transforming growth factor-β, hepatocyte growth factor, epidermal growth factor and hypoxia." (PMID 25586771, 2015). "Binding of HGF to c-MET leads to receptor dimerization and autophosphorylation resulting in the activation of multiple cellular processes that support cancer progression." (PMID 26404380, 2015). "The small molecule kinase inhibitor T-1840383 inhibits both HGF-induced c-MET phosphorylation and VEGF-induced VEGFR-2 phosphorylation in cancer epithelial cells and vascular endothelial cells, respectively." (PMID 28536400, 2015). "The c-Met/HGF signaling cascade is important for morphogenesis during embryonic development and organ regeneration by inducing EMT and can be high-jacked by cancer cells to promote metastasis." (PMID 25886575, 2015). "Our data support the notion that the CAF matrix, particularly for HGF, enhances the pro-survival PI3K/AKT activation and contributes to the chemoresistance of cancer cells." (PMID 26115510, 2015). "Targeting HGF/c-MET signaling has provided valuable tools for the treatment of several malignancies and for overcoming drug resistance in cancer therapy." (PMID 28536400, 2015). "CAFs secrete soluble factors, including TGF-β and HGF, which promote EMT of the neighboring cancer cells via paracrine signaling." (PMID 26473929, 2015). "It has also been shown to maintain the stem cell niche in cancer, with WNT activity in colorectal cancer stem cells described to be supported by myofibroblast-secreted HGF." (PMID 28943627, 2015). "G-MDSCs induce EMT in cancer cells using TGF-β, epidermal growth factor (EGF), and hepatocyte growth factor (HGF)." (PMID 26078490, 2015). "c-Met is a receptor tyrosine kinase that, upon activation by its ligand hepatocyte growth factor (HGF), promotes malignant progression and metastasis in multiple cancers, including HCC." (PMID 25886575, 2015).
cancer (continued). "Although this effect may be associated with the involvement of HGF in the infiltrating growth of cancer cells, this factor could not be evaluated because, to the best of our knowledge, no other study on infiltrating growth patterns was available in the literature." (PMID 25592281, 2015). "This review summarizes the current knowledge regarding proteolytic activation of HGF/SF, its regulation by HAI in cancer tissues, and the possible roles of these proteins in carcinogenesis and cancer progression." (PMID 25268161, 2014). "Met is transiently activated after HGF induction and requires specific CD44 isoforms for its activation in various cancers." (PMID 24823486, 2014). "The c-Met tyrosine kinase receptor (TKR), upon activation by its cognate antigen, hepatocyte growth factor (HGF), generates proliferation, migration, and survival signals in numerous cancers." (PMID 25593979, 2014). "MET encodes a tyrosine kinase receptor whose activation is involved in cancer progression. c-MET is physiologically activated by its natural ligand, hepatocyte growth factor (HGF)." (PMID 24742823, 2014). "To date, a large number of studies demonstrated that HGF/SF-MET signaling is essential for normal development, tissue regeneration and cancer progression." (PMID 25268161, 2014). "The degree of serum HGF and MET expressions in cancer tissues correlates with the prognosis of patients." (PMID 23296269, 2013). "In the initial phase, HGF induces phosphorylation of focal adhesion kinase (FAK) together with a bridge between the ECM and integrins of cancer cells." (PMID 23296269, 2013). "Thus, inhibition of HGF–MET signaling may be a logical strategy to prohibit cancer metastasis." (PMID 23296269, 2013). "It was suggested that cancers driven by WNT-1 signaling would likely be enhanced by SULF1, whereas others, where FGF2 or HGF signaling is the more significant driving mechanism, are inhibited." (PMID 23144729, 2012). "The Met tyrosine kinase, a high affinity receptor for hepatocyte growth factor (HGF), plays a crucial role in controlling invasive growth and is often overexpressed in cancer." (PMID 22408433, 2012). "Hepatocyte growth factor (HGF) is a multifunctional cytokine produced by both stromal and parenchymal cells that stimulates the motility and invasion of several cancer cell types, and induces angiogenesis." (PMID 22741575, 2012). "The HGF/c-MET signaling pathway triggers cell growth and angiogenesis, which are important mechanisms of cancer development, normal growth, and wound healing." (PMID 22438903, 2012). "MACC1 acts as a master regulator of HGF-MET signaling pathway, whose activation has been found to play a critical role in oncogenesis and cancer metastasis." (PMID 22251819, 2012). "HGF then binds with its cognate receptor, c-MET, which is expressed by normal and cancer stem cells." (PMID 22438903, 2012). "As reviewed above, the Nrps interact with several GFs (VEGF, TGF-β, HGF and PDGF) that can all contribute to cancer progression." (PMID 22948112, 2012). "PMN-MDSC were found to express Hepatocyte Growth Factor (HGF) and Transforming Growth Factor-β1 (TGF-β1), while cancer cells were the main source of Epidermal Growth Factor (EGF)." (PMID 21980263, 2011). "Using an antibody proximity-based technology (VeraTag), we describe a novel approach for the detection and quantification of the HGF-c-MET ligand-receptor complex in FFPE specimens including cell lines and human carcinoma tissues." (PMID 21283737, 2011). "We have generated assays to quantify the expression of c-MET, HGF, and HGF/c-MET ligand-receptor complexes in FFPE cell lines and human carcinomas and have cross-validated these measurements using independent biochemical methods." (PMID 21283737, 2011). "Manifold actions for other growth factors and their receptors systems have been described in cancer, e.g. IGF (insulin-like growth factor)/IGFR system and HGF (hepatocyte growth factor)/HGFR systems." (PMID 20565817, 2010).
cancer (continued). "The involvement of HGF in the expression of the ligand/receptor couple CXCL12/CXCR4 has not been studied in EPCs, but we have demonstrated that HGF induces CXCR4 in carcinomas." (PMID 17686146, 2007). "One stromally-derived factor, Hepatocyte Growth Factor (HGF), was found twenty years ago to regulate invasion and growth of carcinoma cells." (PMID 16869958, 2006). "We previously showed that overexpression of a truncated amino-terminal domain of ezrin blocks HGF-induced migration and morphogenesis of epithelial cells, and reduces cell scattering in SP1 carcinoma cells expressing activated c-Src." (PMID 15987432, 2005). "The aim of the present study was initiated to determine the hepatocyte proliferation in relation to the expression of HGF and TGF-alpha in blood and liver tissue of patients with benign and malignant liver tumors after liver resection." (PMID 14960204, 2004). "Human lung fibroblasts, especially when activated into CAFs, secrete cytokines and growth factors (like TGF‐β, IL‐6, PDGF, EGF, HGF, CXCL‐12), ECM proteins, and remodeling enzymes like MMPs and pro‐invasive signals that potentiate cancer stemness and metastasis." (PMID 41537745, 2026). "These pathways are activated by both cancer cells and inflammatory stromal components, emphasizing the necessity for a comprehensive understanding of the interplay between angiogenic (VEGF, HGF) and immunoregulatory (IL-7, LIF) signals to fully comprehend the mechanisms of immune escape." (PMID 41597220, 2026). "Moreover, in BC cell lines, the activation of the HGF pathway through binding of HGF to its receptor c-MET can result in increased cell survival, proliferation, and resistance to cancer inhibitors." (PMID 41597220, 2026). "Finally, we connected HGF, CDK2, FADD, and other proteins to the cancer pathways in the KEGG database." (PMID 40470116, 2025). "Since the co-regulation of STMN1 with HGF and MET protein expression is indicative of a coordinated mechanism, the differential phosphorylation of STMN1 was evaluated to determine its impact on cancer progression and metastasis." (PMID 40723207, 2025). "HGF exerts its biological functions by triggering a cascade of downstream signaling pathways through its receptor, c-MET, which plays a significant role in various types of cancers." (PMID 40520181, 2025). "Given that c-Met inhibition induces senescence-like phenotypes in cancer cells, we hypothesized that SPINT2 promotes senescence through HGF/c-Met suppression." (PMID 40838961, 2025). "Concurrently, markers like HGF, EGF, MMP–1 and the scavenger receptor CD36 reflect processes of chronic inflammation, tissue remodeling, and metabolic reprogramming, which facilitate cancer cell proliferation and survival." (PMID 41194922, 2025). "CAFs-derived HGF inhibits paclitaxel-induced apoptosis of lung cancer cells by increasing the expression of the PI3K/Akt pathway and glucose-regulated protein 78 (GRP78), which supports cancer cell survival and contributes to chemoresistance." (PMID 40136652, 2025). "We hypothesized that inhibition of HGF activation by HAI-1 and HAI-2 may have potential in cancer control." (PMID 40299447, 2025). "Studies have indicated that HGF/MET could enhance this function, suggesting a beneficial impact on anti-cancer immunity." (PMID 40330151, 2025). "HGF has been reported to be highly expressed in pericancerous tissues and the liver; however, not in metastatic cancer cells." (PMID 40076928, 2025). "Agents targeting HGF/c-MET, including small molecules such as crizotinib, tivantinib and cabozantinib, as well as the antibodies like rilotumumab and onartuzumab, have demonstrated efficacy in various cancers." (PMID 40520181, 2025). "Since HGF and MET play important roles in cancer growth and metastasis, and STMN1S16 phosphorylation is regulated by HGF/MET signaling, the NMuMG and DU-145 cell lines were used to determine the impact of STMN1S16 phosphorylation on cell growth, migration, and invasion." (PMID 40723207, 2025).